TCF19 (transcription factor 19)
Diseases named in the same sentence as TCF19 in open-access papers (continued):
Sharing a sentence is not in itself a finding about the gene and the disease.
lymphoma (1 paper, 2025). A malignant (clonal) proliferation of B- lymphocytes or T- lymphocytes which involves the lymph nodes, bone marrow and/or extranodal sites. "WES revealed significantly mutated genes, including several known (NCF1, MMP9, and VDR) and possibly other candidate (CNN2, MUC4, MTSS2, KMT2C, HAVCR2, and TCF19) genes, most of which were associated with the physiological activation of lymphoma cells." (PMID 41296384, 2025).
MALT lymphoma (1 paper, 2025). An indolent, extranodal type of non-Hodgkin lymphoma composed of small B-lymphocytes (centrocyte-like cells). "Similarly, a rs7750641 SNP in the TCF19 gene is a risk variant of MALT lymphoma." (PMID 41296384, 2025).
metastatic disease (1 paper, 2025). "Transcription factor 19 (TCF19) stood out as an unprecedented epithelial gene upregulated in metastatic disease, with prognostic potential and negatively associated with the activity of the androgen receptor." (PMID 40952912, 2025). "Despite these recent advances in the role of TCF19, its contribution to prostate cancer progression, and in particular to metastatic disease, has never been addressed before." (PMID 40952912, 2025).
Obesity (1 paper, 2013). Accumulation of substantial excess body fat. "Dividing donors into lean (BMI < 25) and obese (BMI ≥ 30) categories, we observed a 4.1-fold increase in TCF19 expression (P = 0.0167), similar to the upregulation seen in the B6 mouse with obesity." (PMID 23860123, 2013). "To confirm the regulation of Tcf19 expression by nondiabetic obesity initially identified in a microarray study, we used quantitative RT-PCR to measure Tcf19 expression in response to obesity at 10 wk of age in both the B6 and BTBR strains of mice." (PMID 23860123, 2013). "Because numerous rodent models demonstrate compensatory increases in islet mass in response to metabolic demand, we hypothesized that Tcf19 plays an important role in regulation of obesity-driven β-cell proliferation." (PMID 23860123, 2013). "Combining these traits with our observation that Tcf19 correlates with islet proliferation in obesity and with cell cycle gene expression in mouse islets, we hypothesized that Tcf19 is a transcriptional regulator of β-cell mass." (PMID 23860123, 2013). "We provide evidence that Tcf19 expression is positively correlated with islet expansion in nondiabetic obesity and that Tcf19 expression increases in response to FoxM1 overexpression, a known driver of β-cell proliferation." (PMID 23860123, 2013). "We observed a 3.3-fold increase in Tcf19 mRNA expression (n = 5, P = 0.0005) with obesity in the nondiabetic B6 strain, but this obesity-driven upregulation was not present in the diabetic BTBR strain." (PMID 23860123, 2013). "Tcf19 is expressed in mouse and human islets, with increasing mRNA expression in nondiabetic obesity." (PMID 23860123, 2013).
prostate carcinoma (1 paper, 2025). A carcinoma that arises from epithelial cells of the prostate gland. "In this study, we combine computational and empiric approaches to identify the causal role and prognostic potential of TCF19 in aggressive prostate cancer." (PMID 40952912, 2025). "Gene expression meta‐analysis in multiple prostate cancer patient cohorts identifies Transcription factor 19 (TCF19) as an aggressiveness‐sustaining gene with prognostic potential." (PMID 40952912, 2025). "To assess whether TCF19 could be repressed by AR, we treated AR‐proficient human prostate cancer cell lines with the AR agonist dihydrotestosterone (DHT)." (PMID 40952912, 2025). "To assess whether TCF19 silencing compromises also the proliferation potential of prostate cancer cell lines, we generated stable shRNA expressing PC3, DU145, LnCaP, C4‐2, and 22Rv1 cells." (PMID 40952912, 2025). "In turn, it is tempting to speculate that the upregulation of TCF19 upon treatment with ADT or AR inhibitors could represent a first adaptive response that would support prostate cancer cell function and the eventual acquisition of aggressive features." (PMID 40952912, 2025).
prostate tumors (1 paper, 2025). "TCF19 stood out among the most robust epithelial genes fulfilling these criteria, and we proceeded to study its regulation and the consequences of its perturbation in prostate tumor cells." (PMID 40952912, 2025).
sarcoidosis (1 paper, 2025). Sarcoidosis is a multisystemic disorder of unknown cause characterized by the formation of immune granulomas in involved organs. "Among them, there were 14 genes (ABT1, BTN2A2, C2orf74, CCDC88B, FAM213A, MDH2, METTL21B, PRSS16, RP3-473L9.4, TCF19, TSFM, UBASH3A, UQCC2, ZSCAN26) associated with sarcoidosis risk consistently across these tissues." (PMID 40075078, 2025). "In addition, our TWAS pinpointed many tissue-specific sarcoidosis-associated genes and found expressions of 14 genes (ABT1, BTN2A2, C2orf74, CCDC88B, FAM213A, MDH2, METTL21B, PRSS16, RP3-473L9.4, TCF19, TSFM, UBASH3A, UQCC2, ZSCAN26) associated with sarcoidosis across all three target tissues." (PMID 40075078, 2025).
thyroid cancer (1 paper, 2024). "An important finding was that the C>T variant of rs2073724 partially blocked TCF19’s function and played a protective role in thyroid cancer progression." (PMID 38579171, 2024). "By further leveraging large-scale genetic expression data, we prioritized a key gene, TCF19, which was demonstrated to have a potential causal relationship with thyroid cancer." (PMID 38579171, 2024). "Our study finds that a potential deleterious missense variation (rs2073724) of TCF19 is associated with thyroiditis, and further functional studies demonstrate that this SNP plays a protective role in thyroid cancer development." (PMID 38579171, 2024). "The alternative allele of the rs2073724 variant disrupts the oncogenic functions of TCF19, implicating the rs2073724 C>T variant as a causal genetic variant influencing thyroid cancer risk." (PMID 38579171, 2024). "Our meta-analysis of GWAS and pheWAS data identified an association between TCF19 expression levels and overall survival time in thyroid cancer patients." (PMID 38579171, 2024). "Notably, the alternative allele of the SNP is required for the effect of TCF19 on thyroid cancer progression." (PMID 38579171, 2024). "We demonstrated that TCF19 could promote the progression of thyroid cancer in vitro and in vivo and the C>T variant of rs2073724 disrupted TCF19 protein binding to target gene promoters and their expression, thus reversing the effect of TCF19 protein." (PMID 38579171, 2024). "Based on these results, TCF19 appears to be a potent regulator of thyroid cancer progression, especially in regard to the inflammatory response." (PMID 38579171, 2024). "RNA-seq analysis of TCF19 wild-type and SNP-overexpressing cells illustrated that TCF19 regulates many important biological processes in thyroid cancer, especially the inflammation pathway and the immune response." (PMID 38579171, 2024). "The results indicate that TCF19[C] and TCF19[T] affect the expression of many genes in thyroid cancer cells." (PMID 38579171, 2024). "To detect the function of TCF19 and the SNP in thyroid cancer progression, we established TCF19[C] (rs2073724[C]) expression and TCF19[T] (rs2073724[T]) overexpression in thyroid cancer." (PMID 38579171, 2024). "We also analyzed the TCF19 expression levels in relation to TNM stages in thyroid cancer patients using the TCGA database." (PMID 38579171, 2024). "A CRISPR-Cas9 system to knock-in TCF19[T] in TCF19[C] thyroid cancer cells will lead to more solid results." (PMID 38579171, 2024). "Together, our data suggest that the TCF19 SNP cannot transcriptionally activate oncogenes efficiently, thus playing a protective role in thyroid cancer progression." (PMID 38579171, 2024). "TCGA analysis further demonstrated that TCF19 overexpression affects immune cell infiltration to promote thyroid cancer immune escape and ICB therapy resistance." (PMID 38579171, 2024). "CCK-8 and EdU assays revealed that TCF19[C] overexpression promotes thyroid cancer cell proliferation, and TCF19[T] partly blocked these effects." (PMID 38579171, 2024). "As expected, downregulation of TCF19 suppressed the proliferation, migration, and invasion of thyroid cancer cells compared with control cells, as demonstrated by CCK-8, EdU, Transwell, and wound healing assays." (PMID 38579171, 2024). "As we observed previously TCF19[C] significantly increased the migration and invasion of thyroid cancer cells, while overexpression of TCF19[T] notably reduced these abilities affected by TCF19[C] overexpression." (PMID 38579171, 2024). "To confirm the results of the datasets, we used a quantitative reverse transcription PCR (RT-PCR) method to quantify TCF19 mRNA levels in 10 pairs of thyroid cancer tissues and their corresponding adjacent normal thyroid tissues." (PMID 38579171, 2024). "Our study first highlights that TCF19 and missense variation (rs2073724) of TCF19 are potential prognostic biomarkers for thyroid cancer patients." (PMID 38579171, 2024).
thyroid cancer (continued). "Our study shows that TCF19 regulates many inflammatory pathways in thyroid cancer, such as the TNF signalling pathway and IL-17 signalling pathway." (PMID 38579171, 2024). "Taken together, TCF19 plays an oncogenic role in thyroid cancer progression." (PMID 38579171, 2024). "Furthermore, functional assays and transcriptional profiling in thyroid cancer cells demonstrated that TCF19 regulates important biological processes, especially inflammatory and immune responses." (PMID 38579171, 2024). "Furthermore, in two independent GEO datasets (GSE29265 and GSE33630), TCF19 mRNA levels were significantly higher in thyroid cancer than in matched normal controls." (PMID 38579171, 2024). "Therefore, the potential role of TCF19 and its exonic SNP (rs2073724) in thyroid cancer tumorigenesis and the specific mechanism drew our attention." (PMID 38579171, 2024). "We analysed the TCGA databases and found a positive correlation between TCF19 and immune scores and stromal scores and a negative correlation between TCF19 and tumour purity in thyroid cancer." (PMID 38579171, 2024). "To further investigate the expression pattern of TCF19 in human cancers, we first analysed The Cancer Genome Atlas (TCGA) database and found that TCF19 mRNA levels were upregulated in most human cancers (meta-analysis, log2FC=0.68, P=2.84x10-13) including thyroid cancer." (PMID 38579171, 2024). "Finally, we also need transgenic animal models to demonstrate that TCF19[T] inhibits thyroid cancer progression and promotes inflammatory responses in thyroid cancer." (PMID 38579171, 2024). "Moreover, in vitro and vivo functional studies highlighted that TCF19 plays an oncogenic role in thyroid cancer development, and RNA-seq indicated that TCF19 regulates many important biological processes, especially inflammation pathways." (PMID 38579171, 2024). "Taken together, TCF19 SNPs could induce a strong inflammatory response in thyroid cancer patients with coexistent HT, thus playing a protective role in thyroid cancer progression." (PMID 38579171, 2024). "In addition, we used an exogenous overexpression system to study the function of TCF19 SNPs in thyroid cancer progression." (PMID 38579171, 2024). "Additionally, we conducted RNA-seq to investigate the mechanisms of TCF19 in thyroid cancer progression." (PMID 38579171, 2024). "Furthermore, we constructed TCF19[C] and TCF19[T] overexpression constructs and performed shRNA knockdown experiments to investigate the role of TCF19 in thyroid carcinoma cells." (PMID 38579171, 2024). "Moreover, we performed in vitro functional studies and found that TCF19 could significantly promote the proliferation and metastasis of thyroid cancer and increase the severity of disease progression." (PMID 38579171, 2024). "Taken together, TCF19 may be an exciting new therapeutic target for aggressive thyroid cancer." (PMID 38579171, 2024). "However, the underlying role of TCF19 in the pathology of thyroiditis and thyroid cancer has not been fully investigated." (PMID 38579171, 2024).
urinary system tumors (1 paper, 2022). "In this work, TCF19 was highly expressed in ACC, BLCA, KIRC, PRAD, TCGT, and other urinary system tumors which were under previous findings." (PMID 36111242, 2022).
cancer (15 papers, 2011 to 2026). A tumor composed of atypical neoplastic, often pleomorphic cells that invade other tissues. "Emerging evidence positions TCF19 as a multifunctional regulator associated with cell cycle progression, transcriptional regulation, cancer progression, and immune modulation through epigenetic and signaling mechanisms." (PMID 42072721, 2026). "TCF19 is a growth‐regulated gene that has been increasingly associated with the proliferation potential of multiple cancer types." (PMID 40952912, 2025). "The transcription factor 19 (TCF19) gene has been implicated in conferring a malignant phenotype in cancers." (PMID 38579171, 2024). "The GSVA scores were determined for all tumors to elucidate the molecular mechanism associated with the TCF19 gene associated with pan-cancer." (PMID 36111242, 2022). "The study further constructed the WGCNA net based on the KIRC expression profile for exploring the coexpression network linked with TCF19 in pan-cancer." (PMID 36111242, 2022). "Moreover, genome-wide association studies (GWAS) have indicated that TCF19 increases the risk of certain types of cancer and multiple autoimmune diseases." (PMID 38579171, 2024). "Interestingly, the SNP (rs2073724) located at TCF19 partly abolished its role in cancer progression, and GWAS data showed that the C>T variant of rs2073724 is a deleterious missense variation." (PMID 38579171, 2024). "The factors and mechanisms affecting the sensitivity of antitumor drugs are complex and diverse but results from the analysis of the K-M survival plot revealed that the higher expression group of TCF19 was significantly linked with a shorter prognosis for cancer patients." (PMID 36111242, 2022). "Further substantially downregulated genes include those encoding the transcription factor TCF19, which is associated with cancer cell survival and proliferation, and FAM111B, which encodes the DNA replication-associated serine protease F111B associated with both proliferation and cell cycle control." (PMID 34359681, 2021). "Beyond cancer, TCF19 is involved in metabolic diseases, chronic infections, inflammatory disorders, and sensory deficits." (PMID 42072721, 2026). "TCF19 serves as a promising molecular biomarker for cancer diagnosis, prognosis, and treatment response monitoring, though direct targeting strategies remain unavailable." (PMID 42072721, 2026). "This review provides the first systematic synthesis of TCF19's structural domains, regulatory networks, and context-dependent functions across cancer and non-cancer diseases." (PMID 42072721, 2026). "During the past years, increasing evidence supports the contribution of TCF19 to tumor progression by controlling cellular proliferation in several cancer types through a mechanism that is mediated, at least in part, by targeting the FOXO1 pathway." (PMID 40952912, 2025). "TCF19 is a gene repressed by androgen signaling that sustains core cancer‐related processes such as vascular permeability or tumor growth and metastasis." (PMID 40952912, 2025). "Although the exact molecular mechanism driving this phenomenon remains to be elucidated, our work provides evidence for the role of tumor cell‐expressed TCF19 in vessel homeostasis and permeability, a process that is critical in cancer cell dissemination." (PMID 40952912, 2025). "Herein, we described the expression profile of TCF19 in 33 different cancers and studied the potential regulatory roles of TCF19 for controlling the ccRCC immune microenvironment." (PMID 36111242, 2022). "In 15 kinds of cancers, the TCF19 expression level was significantly related to the follicular helper cells, and in the other 14 kinds of cancers the TCF19 expression level were correlated significantly with the macrophages M1 cell." (PMID 36111242, 2022). "We aimed to study the relationship between transcription factor 19 (TCF19) and cancer immunotherapy in the 33 types of human cancers." (PMID 36111242, 2022).
cancer (continued). "We analyzed the expression level of TCF19 in 33 types of human cancers using the data presented in the TCGA and GTEX datasets." (PMID 36111242, 2022). "The presence of highly expressed TCF19 has been found not only in invasive tumor tissues but also in malignant tumor cell lines." (PMID 36111242, 2022). "TCF19 expression level was significantly related to the CD4 memory-activated cells in 14 kinds of cancers." (PMID 36111242, 2022). "Cancer immunotherapy based on TCF19 can also be explored and the results can potentially open a new avenue for the development of tumor immunotherapy strategies." (PMID 36111242, 2022). "This study provided valuable information on how the TCF19 gene participated in cancer immunotherapy." (PMID 36111242, 2022). "In cancer, TCF19 drives proliferation, metastasis, immune evasion, and therapy resistance." (PMID 42072721, 2026). "Studies report that TCF19 could promote cell proliferation and contribute to the malignant progression of cancer through mechanisms such as regulating WWC1, inhibiting FOXO1, or activating the ATK/FOXO1 signalling pathway." (PMID 38579171, 2024). "Therefore, further research should be conducted to understand how TCF19 influences cancer immunotherapy." (PMID 36111242, 2022). "However, gain-of-function of TCF19 and ATAD2 is associated with cell proliferation in cancer." (PMID 40962957, 2025). "In addition, TCF19 promotes proliferative and migratory capacities of cancer cells." (PMID 41296384, 2025). "Although the correlation between tumor immune microenvironment and TCF19 cannot be applied to all kinds of tumors, our work revealed the immune effects of TCF19 on the microenvironment of specific cancer cells which may potentially help improve the processes of TCRCC targeting therapy." (PMID 36111242, 2022). "Furthermore, as genes with similar expression patterns or functions tending to group together, other genes (e.g., TCF19) in cluster 1 and 2 may also be responsible for important functions in these three cancers and thus are worthy of further attention in future studies." (PMID 21799901, 2011). "It was observed that TCF19 was not significantly influenced by the age (5/33), sex (3/33), or tumor stage (3/21) of cancer patients." (PMID 36111242, 2022).